RNU6-1286P (RNA, U6 small nuclear 1286, pseudogene)
Gene: Small nuclear RNA gene on chromosome 6 (121,354,354 to 121,354,460, forward strand). Ensembl gene ENSG00000206598.
Homologues: Orthologues: chimpanzee U6 (100% identical), macaque U6 (96% identical), rabbit U6 (78% identical). Paralogues in human: RNU6-43P (85% identical), RNU6-812P (85% identical), RNU6-1243P (84% identical), RNU6-1309P (84% identical), RNU6-296P (84% identical), RNU6-1060P (83% identical), RNU6-211P (83% identical), RNU6-1042P (82% identical), RNU6-1152P (82% identical), RNU6-1251P (82% identical), RNU6-140P (82% identical), RNU6-24P (82% identical), and 1286 more.